RNU6-221P (RNA, U6 small nuclear 221, pseudogene)
Gene: Small nuclear RNA gene on chromosome 2 (55,456,106 to 55,456,204, reverse strand). Ensembl gene ENSG00000238493.
Homologues: Orthologues: chimpanzee U6 (99% identical), macaque U6 (94% identical), mouse Gm23378 (75% identical), rat LOC120099400 (75% identical), rabbit U6 (68% identical), pig U6 (67% identical). Paralogues in human: RNU6-775P (87% identical), RNU6-1078P (78% identical), RNU6-1263P (77% identical), RNU6-20P (76% identical), RNU6-38P (76% identical), RNU6-420P (76% identical), RNU6-618P (76% identical), RNU6-1075P (75% identical), RNU6-1122P (75% identical), RNU6-1147P (75% identical), RNU6-15P (75% identical), RNU6-254P (75% identical), and 1288 more.